FABP7 (fatty acid binding protein 7)
Diseases named in the same sentence as FABP7 in open-access papers (continued):
Sharing a sentence is not in itself a finding about the gene and the disease.
Anxiety (continued). "For example, Fabp7-null mice exhibit enhancement of fear memory and anxiety." (PMID 36909794, 2022). "Moreover, hippocampal FABP7 expression was significantly correlated with performance in the battery of anxiety tests." (PMID 36299292, 2022). "Overall, gestational LPS exposure in the F0 generation increased anxiety levels and decreased FABP7 expression levels in the F1 generation, which carried over to the F2 generation, and the intergenerational effects were mainly transferred via the maternal lineage." (PMID 36299292, 2022). "The present study suggested that prenatal inflammation could increase age-related anxiety-like behaviors both in F1 and F2 offspring, and these effects possibly link to the FABP7 expression." (PMID 36299292, 2022). "We hypothesized that LPS exposure during late gestation may affect anxiety-like behaviors in both F1 and F2 offspring in adolescence and midlife, which may be related to altered expression of hippocampal FABP7 protein and messenger RNA (mRNA)." (PMID 36299292, 2022). "Given the potential role of Fabp7 in neurogenesis and anxiety mechanisms, and the role of circadian genes in complex behavior, we examined the expression of Fabp7 throughout the brain and found that it underwent global and coordinated diurnal regulation in astrocytes." (PMID 18286188, 2008). "Importantly, increased anxiety-like behaviors might be related to altered levels of hippocampal Fabp7 expression." (PMID 36299292, 2022). "Therefore, F0 LPS exposure during late gestation may significantly influence hippocampal neurogenesis in F1 mice by reducing Fabp7 expression, thereby increasing age-related anxiety-like behaviors." (PMID 36299292, 2022). "Moreover, the pattern of correlations between anxiety levels and FABP7 mRNA levels was similar." (PMID 36299292, 2022). "Interestingly, Fabp7 was preferentially expressed in numerous astrocytes in the amygdala and septum, regions known to be critically involved in the regulation of fear and anxiety." (PMID 22701680, 2012). "The Fabp3 knockout (KO) mice showed decreased social memory and novelty seeking, and Fabp7 KO mice displayed hyperactive and anxiety-related phenotypes, while Fabp5 KO mice showed no apparent phenotypes." (PMID 25027319, 2014). "Interestingly, FABP7 mice also exhibit increased fear memory and enhanced anxiety without any visible histological abnormalities." (PMID 26148013, 2015). "Similarly, anxiety related behavior is altered in Fabp7 KO mice but in the Fabp7 overexpressing Rev-erbα KO mice this is not the case." (PMID 24932636, 2014).
malignant glioma (12 papers, 2016 to 2025). A grade III or grade IV glioma arising from the central nervous system. "High levels of FABP7 expression have been linked to poor prognosis in various cancers, including malignant gliomas." (PMID 39596296, 2024). "Moreover, FABP7, the gene that codes for the brain fatty acid-binding protein (B-FABP), is upregulated in brain tumor tissue and is associated with a poor prognosis in malignant gliomas due to its effect in inducing cell migration and tumor invasion." (PMID 37509679, 2023). "Published data on the three potential prognostic biomarkers identified, FABP7, MDH1 and RNH1, indicate that high levels of FABP7 are associated with a poor prognosis for patients with various types of tumors, including malignant gliomas." (PMID 38803161, 2024). "In contrast, FABP7-mediated migration in malignant glioma is dependent upon the translocation of FABP7-bound AA to the ER to activate cyclooxygenase 2 (COX-2) dependent pro-migratory and pro-inflammatory pathways." (PMID 35844236, 2022). "FABP7 is highly expressed in patients with malignant glioma; expression levels are positively correlated with worsening pathological grade and poor prognosis." (PMID 32812201, 2020). "In this context, it should be noted that FABP7, which is highly expressed in malignant glioma and GSCs, showed similar expression pattern with that of FASN during the process of GSC differentiation as shown in the present study." (PMID 26808816, 2016). "Fatty acid‐binding protein 7 (FABP7) is highly expressed in GB, and its expression level is negatively correlated with survival in malignant glioma patients; however, the underlying mechanisms of FABP7 involvement in tumor proliferation are still unknown." (PMID 34716958, 2022). "In terms of function, FABP7 is involved in astrocyte proliferation and malignant glioma migration." (PMID 32812201, 2020). "FABP7, a protein involved in the mobilization and transport of fatty acids and with a high affinity for arachidonic and docosahexaenoic acid, is involved in brain development and has been described to improve cell migration and infiltration in malignant glioma cells." (PMID 35328369, 2022). "Among 11 subtypes of FABPs, FABP7 is drastically expressed in GB following previous WHO classifications and its expression level is correlated with malignancy and survival in malignant glioma patients." (PMID 34716958, 2022). "Fatty acid binding protein 7 (FABP7) is an intracellular fatty acid chaperon that is highly expressed in astrocytes, oligodendrocyte-precursor cells, and malignant glioma." (PMID 32812201, 2020). "Nuclear FABP7, which interacts with nuclear receptor PPAR-γ and is important for acetyl-CoA metabolism to modify histone structure in the nucleus, may contribute to metastatic traits of malignant glioma." (PMID 35269427, 2022).
triple-negative breast carcinoma (9 papers, 2014 to 2023). An invasive breast carcinoma which is negative for expression of estrogen receptor (ER), progesterone receptor (PR), and human epidermal growth factor receptor 2 (HER2). "FABP7, which regulates lipid metabolism, has been found to be upregulated in triple negative breast cancer (TNBC) and to affect TNBC cell death as a metabolic mediator in nutrient-depleted conditions." (PMID 35562758, 2022). "It is worth noting that FABP7 expression is upregulated in triple-negative breast cancer." (PMID 37179822, 2023). "Fatty acid-binding protein 7 (FABP7) plays a crucial role in triple-negative breast cancer (TNBC)." (PMID 35743814, 2022). "Similarly, the mRNA level of FABP7 was found significantly higher in triple-negative breast cancer (TNBC) than non-TNBC." (PMID 33292226, 2020).
brain tumors (8 papers, 2008 to 2024). "The upregulation of FABP7 in various cancers, including brain tumors, has been associated with tumor progression." (PMID 39596296, 2024). "We have previously noted associations between the AA:DHA ratio and FABP7 in normal brain and brain tumors." (PMID 26506385, 2015). "Additionally, in human brain tumor specimens, FABP7 expression has been shown to be associated with epidermal growth factor receptor (EGFR) overexpression." (PMID 19014610, 2008). "Our study supports this emerging understanding of the role of nuclear FABP7 in brain tumor development and progression." (PMID 39596296, 2024). "The nuclear FABP7 also regulates genes associated with tumor stemness and metastasis in GBM model studies, underscoring its transactivational role in brain tumor progression." (PMID 39596296, 2024). "Despite growing evidence for FABP7’s tumor-intrinsic onco-metabolic functions, its mechanistic role in regulating the brain tumor immune microenvironment (TIME) and its impact on prognosis at the molecular level remain incompletely understood." (PMID 39596296, 2024). "Increase of n-3 fatty acid content of brain tumor tissues in present study accompanied by increase in mRNA levels of FABP7." (PMID 19014610, 2008). "Overall, these findings suggest that FABP7 may play a significant role in the regulatory network of genes promoting brain tumor development, especially in LGG." (PMID 39596296, 2024). "Consistent with in vitro results, the levels of acetyl‐CoA and ACLY activity were upregulated in FABP7wt compared to control, but not changed in FABP7mut, suggesting that the interaction between FABP7 and its ligands regulates caveolin‐1 expression through histone modification in brain tumors." (PMID 34716958, 2022). "Dietary supplementation of DHA containing oil could be an effective way to increase levels of long chain n-3 fatty acids in brain tumors and this increase may be mediated partly by up-regulation of FABP7 expression." (PMID 19014610, 2008). "Supplementation of DHA containing oil could increase long chain n-3 fatty acid content of brain tumors and part of this increase may be mediated by increase in expression of FABP7." (PMID 19014610, 2008). "Furthermore, pERK positivity was upregulated in FABP7wt‐expressing tumor compared to control and FABP7mut‐expressing tumor, suggesting that the interaction between FABP7 and its ligands boosted the tumor proliferation through activated intracellular cell signaling in brain tumors." (PMID 34716958, 2022). "In our study, although DHAO feeding increased FABP7 mRNA levels of rat's brain tumors, it did not affect EGFR expression." (PMID 19014610, 2008). "While these cell lines offer valuable insights into FABP7 expression, they may not fully represent the heterogeneity seen across different types and grades of brain tumors." (PMID 39596296, 2024).
Alzheimer disease (7 papers, 2021 to 2025). A progressive, neurodegenerative disease characterized by loss of function and death of nerve cells in several areas of the brain leading to loss of cognitive function such as memory and language. "FABP7 is also proposed to functionally interact with sortilin, the neuronal receptor for apolipoprotein E (apoE), with apoE3 leading to expression of FABP7 but the apoE4 variant, a major risk factor for Alzheimer’s disease, being associated with reduced FABP7 levels." (PMID 37207357, 2023). "FA-specific roles for FABP7 have been proposed to mediate effects in Alzheimer’s disease, with AA binding stimulating inflammatory pathways and DHA imparting neuroprotection." (PMID 37207357, 2023).
amyotrophic lateral sclerosis (7 papers, 2020 to 2025). Amyotrophic lateral sclerosis (ALS) is a neurodegenerative disease characterized by progressive muscular paralysis reflecting degeneration of motor neurons in the primary motor cortex, corticospinal tracts, brainstem and spinal cord. "We recently showed that upregulation of fatty acid binding protein 7 (FABP7) expression in primary spinal cord astrocyte cultures induces a proinflammatory phenotype that could contribute to the neurotoxicity observed in amyotrophic lateral sclerosis." (PMID 37688656, 2024). "However, in pathological contexts such as amyotrophic lateral sclerosis (ALS), FABP7 upregulation promotes NF-κB-driven pro-inflammatory signaling and astrocytic neurotoxicity, while its silencing reduces motor-neuron toxicity, underscoring its dual and context-dependent nature." (PMID 41462664, 2025).
astrocytoma (7 papers, 2005 to 2024). "The correlation between IDH1 status and FABP7 expression level in astrocytoma, oligodendrocytoma, and oligodendroglioma analyzed using TCGA database." (PMID 34716958, 2022). "FABP7 is highly expressed at the site of infiltration and surrounding vessels in high grade astrocytoma and down-regulation of its expression in GSCs by small interfering RNAs significantly reduces cell proliferation and migration." (PMID 26808816, 2016). "We found that 1 of 5 grade II astrocytoma specimens and 3 of 5 grade III astrocytoma specimens were positive for FABP7." (PMID 16623952, 2006). "FABP7 expression can be found in all grades of astrocytoma, but neoplastic cells with nuclear FABP7 were only seen in infiltrative types of tumors." (PMID 16623952, 2006). "Furthermore, when we evaluated in separated samples including astrocytoma, oligodendrocytoma, and oligodendroglioma, high frequency of FABP7‐upregulated expression was observed in IDH1wt of all types of tumors (19 of 20 in astrocytoma, 6 of 6 in oligodendrocytoma, 2 of 2 in oligodendroglioma)." (PMID 34716958, 2022). "Because FABP7 demonstrates increased expression and variable subcellular localization in a subset of reactive astrocytes but not in most oligodendrocytes, we determined whether FABP7 is universally expressed in different grades of astrocytoma." (PMID 16623952, 2006). "The presence of nuclear FABP7 immunoreactivity in grades II, III, and IV astrocytoma specimens was statistically significant when compared to grade I pilocytic astrocytoma." (PMID 16623952, 2006). "FABP7 is preferentially expressed in cells of astrocytic features, and demonstrates variable expression levels and subcellular localization in gliotic tissues and all grades of astrocytoma, indicating that FABP7 expression alone does not contribute to malignant progression of astrocytomas." (PMID 16623952, 2006). "Although FABP7 expression does not predict the outcome of patients with ODG and OAC, FABP7 may have prognostic value for grade II and grade III astrocytomas due to its heterogeneous patterns of expression and subcellular localization in these two tumor types." (PMID 16623952, 2006).
diffuse large B-cell lymphoma (7 papers, 2015 to 2025). "An LTR transcript in diffuse large B-cell lymphoma (DLBCL), encoding fatty acid binding protein 7 (FABP7), promotes cancer development." (PMID 41459148, 2025). "The first study reported activation of the colony stimulating factor 1 receptor (CSF1R) gene in Hodgkin’s lymphoma and the second reported activation of the fatty acid binding protein 7 (FABP7) gene in diffuse large B-cell lymphoma." (PMID 25821520, 2015). "For instance, in tissues from patients with diffuse large B-cell lymphoma (DLBCL), LTR2 activity drives the formation of a chimeric isoform of the Fatty Acid-Binding Protein 7 (FABP7) gene." (PMID 39770638, 2024). "A comprehensive approach in diffuse large B-cell lymphomas (DLBCLs) has detected multiple LTR transcripts in several genes, including fatty-acid binding protein 7 (FABP7); that are known to promote lymphomagenesis." (PMID 28471386, 2017). "In diffuse large B-cell lymphoma (DLBCL), a chimeric transcript initiated by the activation of an LTR2 element leads to the expression of the modified form of Fatty Acid-Binding Protein 7 (FABP7)." (PMID 40328728, 2025). "Similarly, cancer-specific isoform expression of the fatty acid binding protein 7 (FAB7) gene that is normally active in brain, is sustained by an LTR (LTR2-FABP) in diffuse large B-cell lymphoma." (PMID 25927889, 2015).
renal carcinoma (7 papers, 2011 to 2024). A carcinoma arising from the epithelium of the renal parenchyma or the renal pelvis. "FABP7 overexpression in renal cancer cells triggered a pronounced proliferation rate and activated signal transduction pathways associated to ERK kinase and STAT3 signalling." (PMID 32856199, 2020). "We chose to study the TUHR14TKB cell line, because it expresses higher levels of FABP7 than other cell lines derived from renal carcinomas (OS-RC-2, 786-O, 769-P, Caki-1, and ACHN)." (PMID 28292269, 2017).
renal cell carcinoma (5 papers, 2009 to 2018). "Renal cell carcinomas (RCCs) overexpress fatty acid binding protein 7 (FABP7)." (PMID 28292269, 2017). "FABP7 was shown to be a specific biomarker for renal cell carcinomas." (PMID 27779102, 2016).
autism (4 papers, 2014 to 2025). Persistent deficits in social interaction and communication and interaction as well as a markedly restricted repertoire of activity and interest as well as repetitive patterns of behavior. "Further investigation demonstrated that both Fabp7 knockout and Mek2 overexpression in mice resulted in autism-related repetitive, stereotyped behaviors and social deficits, strongly linking FABP7/MEK pathway abnormalities to ASD pathogenesis." (PMID 41359105, 2025). "Here, we show that the premature differentiation of NSCs over time is regulated by the FABP7/MEK pathway in organoids derived from individuals with idiopathic non‐regressive autism accompanied by normocephaly." (PMID 39556706, 2024). "The results revealed that the Fabp7 KD mice buried more marbles than the control mice did, which strongly suggested that the Fabp7 KD mice exhibited autism‐related behaviors." (PMID 39556706, 2024). "Taken together, these findings indicate that MEK2 overexpression in the hippocampus causes autism‐related behaviors, whereas MEK2 inhibits could reverse deficits in cortical differentiation in ASD organoids, indicating that the FABP7/MEK pathway may play an important role in the pathogenesis of ASD." (PMID 39556706, 2024). "Moreover, both Fabp7‐knockdown and MEK2‐overexpressing mice exhibited social behaviors indicative of autism." (PMID 39556706, 2024). "Moreover, both Fabp7‐knockdown and MEK2‐overexpressing mice exhibited repetitive stereotyped behaviors and social defects relevant to autism." (PMID 39556706, 2024).
breast tumors (4 papers, 2008 to 2021). "Our results confirmed partially a higher frequency of FABP7 positives in TNBC group (∼19%) as compared to the other subtypes of breast tumors." (PMID 25389781, 2014). "In conclusion, HMGCS2 and FABP7 are novel protein markers for apocrine differentiation that are highly conserved among apocrine breast tumors retaining their expression during tumor progression." (PMID 25389781, 2014). "Our results validated a higher frequency of FABP7 expression in basal-like/TNBC subtypes, as compared with other phenotypes or molecular subtypes of breast tumors." (PMID 33292226, 2020). "FABP7 positives were found in 78% of all IAC cases and in 96% of ADCIS and only in 14 out of the 210 non-IAC breast tumor subtypes (6,6%)." (PMID 25389781, 2014).
Down syndrome (4 papers, 2007 to 2022). "FABP7 is overexpressed in Down syndrome adult and fetal brains, whereas FABP3 is significantly decreased in Down syndrome adult brains." (PMID 34208549, 2021). "Fatty acid-binding protein 7 (Fabp7), which is elevated in Down syndrome fetal brains, was found to be upregulated in dnADAM10 mice by microarray analysis." (PMID 19196476, 2009). "Overexpression of the dominant-negative form dnADAM10 led to a significant increase in the expression of the fatty acid-binding protein Fabp7, which also has been found in higher amounts in brains of Down syndrome patients." (PMID 19196476, 2009). "Increased amounts of Fabp7 in the brains of individuals with Down syndrome suggest that higher concentrations of Fabp7 contribute to brain abnormalities and mental retardation." (PMID 19196476, 2009). "Furthermore, FABP7 upregulation correlates with PKNOX1 gene-dosage imbalance in the brains of Down syndrome patients." (PMID 34208549, 2021). "Since in Down syndrome patients α-secretase activity significantly decreases with age, our results provide a connection between inhibition of α-secretase (in our study by dnADAM10) and upregulation of Fabp7." (PMID 19196476, 2009).
ependymoma (4 papers, 2007 to 2023). A WHO grade II, slow growing tumor of children and young adults, usually located intraventricularly. "However, normal glial cells and glia-like tumor cells have their specific lineage-associated genes, such as FABP7 and MSX1 in normal ASCs, OLIG2 and OPCML in normal OPCs and OLs, FRMD5 in ASC-like ependymomas and GLUL in OPC/OL-like ependymomas." (PMID 37095395, 2023). "In this study, we demonstrate that brain lipid binding protein (BLBP, FABP7) is expressed in a sub-population of cells in ependymoma patient samples, consistent with it being a cancer stem cell marker." (PMID 33925302, 2021).
metastatic melanoma (4 papers, 2008 to 2021). A melanoma that has spread from its primary site to another anatomic site. "For example, primary versus metastatic melanomas express higher FABP7 mRNA levels." (PMID 21771320, 2011). "In the clinical specimens, FABP7 protein expression was highest in nevi, with no observed differences between primary and metastatic melanoma." (PMID 18826602, 2008).